IL1B (interleukin 1 beta)
Diseases named in the same sentence as IL1B in open-access papers (continued):
Sharing a sentence is not in itself a finding about the gene and the disease.
COVID-19 (continued). "Excessive and uncontrolled releases of pro-inflammatory cytokines such as IL1B were increased in severe corona-virus disease 2019 (COVID-19) patients." (PMID 37147350, 2023). "Accumulating evidence showed that increased IL-1β/TNF-α/IL-8 in the serum of patients with COVID-19, compared to those in HC subjects." (PMID 37904132, 2023). "Studies have found an increase in the circulatory IL-1β level at different stages of COVID-19, including in mild SARS-CoV-2 infection, but this cytokine had a late peak 2–3 months after infection." (PMID 37484856, 2023). "AMP, along with the daily practice of SKY, during normal life (pre-COVID-19 phase) reduced mRNA expression of IL1β, IL6, and TNF and increased mRNA expression of SOD, catalase, and GPx." (PMID 37546047, 2023). "Convalescent COVID-19 children had elevated levels of IFNγ, IL-2, TNFα, IL-1α, IL-1β, IFNα, IFNβ, IL-6, IL-12, IL-17A and G-CSF in comparison to control children." (PMID 37013538, 2023). "Future studies should delve deeper into investigating the role of IL-1β in trained immunity following COVID-19." (PMID 38090572, 2023). "Recent studies revealed heightened levels of inflammasome-associated products, IL-1β, IL-18, and LDH in COVID-19 patients, highlighting the inflammasome’s association with the disease." (PMID 37868953, 2023). "Administration of nano-curcumin has been reported to provide anti-viral action and to downregulate expression and secretion of the inflammatory cytokines IL-1β and IL-6 in COVID-19 patients." (PMID 37359549, 2023). "Vector analysis conducted in the 1st trimester indicated that CXCL8, CCL3, CCL5, IL-1β, TNF-α, IL-12, IL-15, IL-1Ra, IL-10, and G-CSF were associated with convalescent COVID-19 in pregnant women." (PMID 37122732, 2023). "Pyroptosis was found in COVID-19 patients with increases of IL-1β and IL-18, which further promoted the secretion of pro-inflammatory cytokines such as IL-6, IFN-γ, MCP-1/CCL2, MIP-1α/CCL3, MIP-1β/CCL4." (PMID 37631016, 2023). "Recent studies show that an abnormal diffuse inflammatory cytokine profile can persist in long COVID-19 subjects for at least 8 months, along with the persistent deregulation of IL-1β, IL-6, and TNF-α." (PMID 37887357, 2023). "Inflammatory mediators primarily associated with the cytokine storm in COVID-19 patients such as TNF-α, IL-1β, IL-6, IL-8, VEGF, and GM-SCF were elevated in both apical and basal media." (PMID 37200377, 2023). "Then, this activation leads to the increase of several inflammatory interleukins (such as IL-1β and IL-6) that are responsible for adverse clinical outcomes in COVID-19." (PMID 37674935, 2023). "Amongst those with acute COVID-19, eleven markers significantly differed across disease severity categories: IL-1β, IL-2, IL-6, IL-10, IL-18, IL-23, IL-33, TNF-α, IP-10, G-CSF and YKL-40." (PMID 37063871, 2023). "Mitochondrial ROS mediate various signaling pathways, increase the expression of inflammatory cytokines (IL-6, IL-1β, TNF-α, etc.), and increase the risk of thrombosis in patients with COVID-19." (PMID 37834324, 2023). "A second sizable study analyzed plasma IL-1β in 168 COVID-19 patients and revealed a median 1.52 pg./mL." (PMID 37928695, 2023). "In the same line with IL-1β the level of IL-8, miRNA-618 and miRNA-16–2-3p show a significantly increase level in the COVID-19 positive patients." (PMID 37222789, 2023). "Consistent with previous reports, COVID-19 patients displayed higher levels of TNFα, IL-1β, IL-6, IFNα, IFNβ, TGFβ and IL-10 in comparison with HD." (PMID 37063865, 2023). "All genes were highly expressed in COVID-19 individuals when compared to the control group except for IL1B." (PMID 37389217, 2023). "Of note, IL-8 and IL-1B signatures in the inflPASC cohort well-exceeded levels seen in severe/critical COVID-19 patients sampled in the acute phase of disease suggesting an inflammatory process unique to the recovery phase in this cohort." (PMID 37452024, 2023).
COVID-19 (continued). "According to a retrospective study, subcutaneous administration of canakinumab (anti-IL-1β) decreased hyperinflammation and improved PaO2/FiO2 ratio in COVID-19 patients." (PMID 36793739, 2023). "Other cytokines, including TNF-α, IFN-γ, and IL-1β, have also been involved in the intense cytokine release described in COVID-19 patients, contributing to the proinflammatory state and hypercoagulability." (PMID 37628963, 2023). "TNFα, IL1β and IL6 are known to be associated with post-acute sequelae of COVID-19 and used as biomarkers of SARS-CoV-2 infection in previous study." (PMID 36697403, 2023). "Human neutrophils were treated with plasma–derived EVs from COVID-19 patients or HC subjects for 24 h; the supernatants were collected and the levels of IL-1β/TNF-α/IL-8 were analyzed using ELISA." (PMID 37904132, 2023). "In COVID-19, the lung’s epithelial injury leads to the secretion of IL-1α and the production of IL-1β." (PMID 37756264, 2023). "Production of IFN-γ, IP-10, and IL-1β, amongst others, in response to Mtb-antigen stimulation was impaired in the whole blood from coinfected active TB disease/COVID-19 patients." (PMID 37545508, 2023). "In the prospective, longitudinal cohort study, excessive production of IL-1β, IL-6, IL-8, transforming growth factor-β, interferon-α, and interferon-γ was observed in the semen of patients with COVID-19 during a 60-day research period." (PMID 37958725, 2023). "PPI network and core target analysis indicated that IL-6, TNF, MAPK1, and IL1B were the key targets against COVID-19." (PMID 38018195, 2023). "The cytokine storm of COVID-19 patients (with an elevation of IL-1β, IL-6 and TNF-α) has been related to the increase of eicosanoids including AA and its metabolites." (PMID 36984782, 2023). "Convalescent COVID-19 children had elevated levels of IFNγ, IL-2, TNFα, IL-1α, IL-1β, IFNα, IFNβ, IL-6, IL-12, IL-17A, IL-10 and G-CSF in comparison to control children." (PMID 37013538, 2023). "Canakinumab is a recombinant human antibody designed to neutralize IL-1β biological action, and it has been assessed as a possible COVID-19 therapy." (PMID 37928695, 2023). "Studies have shown that the NLRP3 inflammasome is active and there are high levels of IL-1β and IL-18 in COVID-19 patients." (PMID 37631016, 2023). "Immune cell activation is reflected by high levels of IL-6, IL-1β, IL-18 known as the COVID-19 cytokine storm." (PMID 36776845, 2023). "To derive perspective on blood IL-1β concentrations in COVID-19, we calculated the weighted average of median IL-1β concentrations in the 2,187 patients described in the studies above." (PMID 37928695, 2023). "Increased cytokine levels in COVID-19 including IL-1β, IL-6, interferon-inducible protein 10 (IP-10), TNF-alpha, IFN-γ, macrophage inflammatory protein (MIP) 1α and 1β, and vascular endothelial growth factor (VEGF) were observed." (PMID 37753372, 2023). "Resveratrol is also able to decrease the effect of proinflammatory cytokines such as IFN-γ, TNF-α, and IL-1β, which are important factors in the onset of the cytokine storm in COVID-19." (PMID 37299603, 2023). "Several preclinical studies reported that the type I IFN response co-occurs with proinflammatory cytokine responses such as TNF-α and IL-1β, which is a major feature of severe COVID-19." (PMID 36989209, 2023). "The majority of studies have reported that proinflammatory cytokines, such as interleukin (IL)-6, tumor necrosis factor α (TNFα), and IL-1β, are related to COVID-19 pathogenesis." (PMID 37515185, 2023). "Increased levels of IL-1β/TNF-α/IL-8 were released from human neutrophils after being stimulated with COVID-19 patient–derived EVs, compared to those in control cells." (PMID 37904132, 2023). "This study found that there are activated endothelial cells and high levels of biomarkers of blood vessel damage (ICAM-1, ANGPT-2, IL-1β) in severe COVID-19 cases." (PMID 36992415, 2023).
COVID-19 (continued). "Acute COVID-19 children had significantly elevated levels of cytokines, IFNγ, IL-2, TNFα, IL-1α, IL-1β and IFNα in comparison to convalescent children." (PMID 37013538, 2023). "Upstream regulator analysis showed strong activation scores for many cytokines, including IFNs, TNF, and IL-1β, in the T/NK cells of patients with COVID-19." (PMID 37606044, 2023). "IL-1α, IL-1β and ferritin were relatively increased in patients with COVID-19, particularly when compared with CAP-other and CAP-flu, whilst procalcitonin, IL-6 and CRP were highest in CAP-strep." (PMID 35660785, 2022). "SASP components include the proinflammatory cytokines IL-1β and IL-6, which are elevated in plasma of COVID-19 patients that have acute respiratory distress syndrome or systemic inflammatory features." (PMID 35086840, 2022). "A small study showed an increase in IL-1β in COVID-19 patients correlating with the severity of the disease but a larger study of roughly 1500 patients in New York has not found significant contributions of IL-1β." (PMID 35548445, 2022). "Systemic values of IL-1β (p = 0.001), IL-6 (p = 0.001), IL-10 (p = 0.026), IL-23 (p = 0.001), IL-33 (p = 0.001), and Gal-1 (p = 0.001) were significantly higher in COVID-19 patients in stage III compared to patients in stage I and II." (PMID 35075140, 2022). "Exposure of COVID-19 exosomes significantly increased the IL-1β level in the culture medium of HMEC-1 compared with the exosomes from healthy donors treated HMEC1 culture medium." (PMID 35587188, 2022). "A not yet published study showed a long-lasting cytokine signature in patients with prior COVID-19 where IL-1β, IL-6, and TNF-α showed a significant correlation with post-acute COVID-19." (PMID 35883640, 2022). "Other therapeutic monoclonal antibodies are directed at proinflammatory cytokines (IL-6, IL-1β, TNF and GM-CSF) to mitigate cytokine storm syndrome (CSS) that is the frequent cause of fatal acute respiratory distress syndromes (ARDS) in COVID-19 patients." (PMID 35743031, 2022). "These common genes were mainly involved in the inflammatory process caused by COVID-19-related cytokines, such as IL6 and IL1β." (PMID 35165525, 2022). "The COVID-19 group had significantly higher plasma levels of IL-1β, IL-4, IL-7, IL-8, IL-12, TNF, IP-10, eotaxin, GM-CSF, bFGF, and the complement activation products TCC and C3bc, as compared to the non-COVID-19 group." (PMID 35222429, 2022). "Our results agree with these conclusions; COVID-19 patients with severe illness and poor prognosis had lower levels of IL-1B, IL-2, and IL-8 than COVID-19 patients with good prognosis." (PMID 36294868, 2022). "Peripheral immune response and increased cytokine production, including an early surge in TNF and IL-1β concentrations activate glia, leading to aggravation of neuroinflammation and dysfunction of neurons during COVID-19." (PMID 36230921, 2022). "In this study of 90 ICU COVID-19 patients, we evaluated serum levels of four cytokines (IL-1β, IL-6, IL-10 and TNFα) as well as standard clinical and laboratory measurements." (PMID 36451808, 2022). "Among COVID-19 patients, the most common disorders of cytokines and chemokines are increased levels of IL-1β, IL-2, IL-6, interleukin-7 (IL-7), IL-10, TNF-α, CRP, chemokine ligand 2 (CCL2), as well as an increase or decrease in the concentration of IFN-γ." (PMID 36294388, 2022). "The most probable cause of IDO enzyme activation in COVID-19 is the increased level of pro-inflammatory cytokines including IFN-γ, IL-1β and IL-6 and activated oxidative stress pathways, which both potently stimulate IDO." (PMID 35840908, 2022). "In fact, IL-1β levels present in COVID-19 patients were statistically higher compared to the control group." (PMID 36422642, 2022). "The COVID-19 mRNA vaccine encodes the SARS-CoV-2 spike protein, which triggers IL-1β secretion in macrophages." (PMID 35746474, 2022).
COVID-19 (continued). "We observed a significant induction of NLRP3, caspase-1, and interleukin-1β (IL-1β) mRNA expression in endothelial cells following exposure to exosomes from severe COVID-19 patients compared with that from patients with mild disease or healthy donors." (PMID 35587188, 2022). "Pro-inflammatory signatures of severely affected COVID-19 patients feature elevations of interleukin-1β (IL-1β), IL-6, and tumor necrosis factor alpha (TNF-α)." (PMID 35600840, 2022). "In patients with severe COVID-19, a strong activation of alveolar macrophages and very high pulmonary concentrations of proinflammatory mediators (IL-6, IL-8, IL-1β) and chemokines were found." (PMID 35457086, 2022). "IL1B, P2RX7, IFNB1, IFNB1, TNF, and CASP1 enhance the network connectivity between multiple sclerosis (MS) complex genomes associated with COVID-19 and NOD-like receptor (NLR) signaling." (PMID 36483456, 2022). "We observed a significant increase in mRNA expression of NLRP3, pro-caspase-1 (CASP1), and pro-IL-1β genes in HMEC-1 cells exposed to exosomes from the plasma of severe COVID-19 patients compared with that from healthy subjects." (PMID 35587188, 2022). "An interesting randomized controlled trial on forty COVID-19 patients supplemented with nano-curcumin showed a significant reduction in IL-1β and IL-6 expression and secretion." (PMID 35011106, 2022). "A third module (c) revolves around TNF and includes IL1A, IL1B, TNFSF14, TNFAIP3, and CSF2 that likely mediates the inflammatory response associated with COVID-19 progression." (PMID 35085325, 2022). "When stimulated in vitro, the monocytes from COVID-19 patients synthesized significantly lower levels of pro-inflammatory cytokines IL-1β, TNFα, IL-6, and MCP-1, compared to the cells obtained from apparently healthy donors." (PMID 35632823, 2022). "Further, we found that monocytes and LDNs of COVID-19 convalescents recovered from Omicron infection were imprinted with IL-1β- or IFN- responsive signatures." (PMID 36379915, 2022). "SARS-CoV-2 directly or indirectly triggers inflammasomes, leading to the secretion of pleiotropic IL-1 family cytokines (IL-1β and IL-18), although the molecular mechanisms for COVID-19 disease pathogenesis remain poorly understood." (PMID 35587188, 2022). "These cell types are also responsible for the pro-inflammatory state observed in COVID-19, and this is consistent with the higher levels of IL-1β, IP-10 and IL-5 observed in the critical COVID-19 group compared to the septic shock group." (PMID 36008932, 2022). "By contrast, we observed IL-1β protein levels that are 15-fold higher in COVID-19 infected hamster lungs versus mock-infected controls." (PMID 36614003, 2022). "Supernatants were subsequently analyzed for key inflammatory cytokines associated with the cytokine storm in COVID-19 (IFN-γ, IL-1β, IL-2, IL-4, IL-6, IL-8, IL-10, IL-12p70, IL-13, and TNF-α), using the Meso Scale platform." (PMID 36296272, 2022). "In this review, we summarize current evidence supporting the pathogenetic role of the NLRP3 inflammasome and IL-1β in COVID-19, and discuss clinical trials testing IL-1 inhibition in COVID-19." (PMID 36209522, 2022). "Predictors of disease severity include ferritin, TNF-α, IL-8, IL-1β and IL-6, suggesting that hyperinflammation is driving COVID-19 severity and death." (PMID 35244141, 2022). "The mRNA expression of the products of the inflammasome activation, such as IL-1β and IL-18, was overexpressed in COVID-19/B.1 patients (p < 0.0001 vs. control patients) and overexpressed in COVID-19/B.1.1.7 (p < 0.0001 vs. COVID-19/B.1 patients)." (PMID 36498845, 2022). "Similar to dengue, those who proceed to develop severe COVID-19 have high levels of many proinflammatory cytokines such as IL-6, IL-1β, IL-10, CXCL-10, MCP-1 and the cytokine storm is shown to associate with both severe dengue and COVID-19." (PMID 35786403, 2022).
COVID-19 (continued). "As evidence was mounting, a pathogenetic role for the NLRP3 inflammasome/IL-1β signalling pathway in COVID-19 was established." (PMID 36209522, 2022). "Caspase 1 cleaves inactive pro-IL-1β to active IL-1β which is an important mediator for lung inflammation and fibrosis in COVID-19." (PMID 36422492, 2022). "The COVID-19 group had significantly higher plasma levels of IL-1β, IL-4, IL-7, IL-8, IL-12, TNF, IP-10, eotaxin, GM-CSF, bFGF, complement TCC and C3bc, and significantly lower levels of IL-13 and MIP-1α, as compared to controls." (PMID 35222429, 2022). "The levels of IL-6 and IL-1β are increased in patients with COVID-19, and it has been reported that IL-6 and IL-1β are involved in platelet hyperactivation." (PMID 35907817, 2022). "COVID-19 patients have high levels of pro-inflammatory cytokines and chemokines such as IL-1β, IL-2, IL-6, IL-7, IL-10, IFN-γ, TNF-α, G-CSF, CCL2, and CXCL10." (PMID 35782361, 2022). "Both COVID-19 groups demonstrated a significant elevation (p < 0.001) in IL-1β, IL-4, IL-10, IL-17, and IFN-γ as compared to healthy controls." (PMID 35891209, 2022). "Second, the lack of detection results of glycosylated hemoglobin A1C, insulin level, TNF-α, IFN, IL-1β, and other cytokines limited the deeper assessment of glycemia and immune dysfunction in COVID-19 patients with T2DM." (PMID 37359706, 2022). "Similar to the BALF findings, the authors found that peripheral blood mononuclear cells (PBMCs) from COVID-19 patients exhibit a transcriptional upregulation of prototypical signaling ligands with known hDRG receptors, including IL-1β and TNF." (PMID 35281455, 2022). "There is evidence that many pro-inflammatory cytokines and chemoattractant are elevated in COVID-19 patients, including IL-1β, IL-6, IL17, TNF-α, GM-CSF, and IFN-γ." (PMID 36034704, 2022). "Serum IL-1β and IL-18 levels were also positively correlated with each other in patients with COVID-19 (Spearman’s r = 0.30, p = 0.0028)." (PMID 34997207, 2022). "Compared with controls, patients with COVID-19 had higher serum concentrations of all biomarkers except IL-12p70 and IL-1β (eTable 2 and eFigure 2 in the Supplement)." (PMID 35604688, 2022). "The receiver operator characteristic (ROC) curve analysis indicated that IL-1β, IL-4, IL-18, and IL-35 were fair (acceptable) predictors for COVID-19 in moderate cases." (PMID 36675695, 2022). "Stimulation of peripheral blood mononuclear cells (PBMC) from patients with severe COVID-19 have shown an increased secretion of IL-1β." (PMID 36096831, 2022). "It is reported that patients with COVID-19 symptoms have higher levels of cytokines and inflammatory markers such as IL-6, IL-8, IL-1β, IL-10, IL-12, and IFN-γ." (PMID 35847031, 2022). "We performed quantitative real-time PCR (qRT-PCR) for representative COVID-19 related host inflammatory cytokine genes and found that a cytokine panel (including IL-6, IL-1β, TNF-α, CCL2, and CXCL9) was induced by SARS-CoV-2 infection." (PMID 34979342, 2022). "IL1-β has a key role in the pathogenesis of COVID-19; hence, blocking IL1-β-mediated activity is a reasonable therapeutic strategy." (PMID 35619180, 2022). "Further, impaired T cell function, increased release of inflammatory mediators, especially TNFα and IL-1β, and elevated levels of ACE2 also played a crucial role in developing severe COVID-19 symptoms and predisposed to higher mortality risk." (PMID 36589459, 2022). "Patients infected with COVID-19 harbour an expanded population of circulating monocytes that secrete IL-6 and IL-1β, as a result, patients with COVID-19 have elevated serum IL-6 as well as lactate dehydrogenase levels compared with healthy controls." (PMID 35843719, 2022). "Since the inflammasome-dependent cytokine IL-1β is also elevated in patients with COVID-19, drugs that block IL-1 signaling can potentially interrupt inflammatory responses and have been tested." (PMID 36419185, 2022).